IFNG (interferon gamma)
Diseases named in the same sentence as IFNG in open-access papers (continued):
Sharing a sentence is not in itself a finding about the gene and the disease.
cancer (continued). "We applied this pipeline to our large-scale, mechanistic pan-cancer signaling model (named SPARCED) and demonstrate it by adding an IFNγ pathway submodel." (PMID 35729113, 2022). "After restimulation with B16F10 cancer cells, ~10% of CD8+ T cells in TdLNs from mice treated with the hydrogel secreted IFNγ, significantly higher than those from mice receiving other treatments." (PMID 35780226, 2022). "Gene ontology analysis also indicated that IFNG, TNFRSF1A and CD3 are involved in the positive regulation of tyrosine phosphorylation of STAT proteins, which are known to be involved in cancer and inflammation." (PMID 35745107, 2022). "As interferon-gamma upregulates PD-L1 via the JAK-STAT pathway, the TIS score is also a highly effective prognostic and predictive marker for ICI benefit in pan-cancer analysis." (PMID 36177003, 2022). "In tumor microenvironment, the released IFNγ from CD8(+) T cells suppresses SLC3A2 and SLC7A11 expression on cancer cells, consequently facilitates cancer cell accumulation of lipid peroxidation and ferroptosis." (PMID 36289191, 2022). "The anti-viral or anti-cancer activity of CD8+ T cells is mediated by a polyfunctional Type1 cytokine response (e.g., IL-2, IFNγ, and TNFα)." (PMID 36619639, 2022). "Regarding changes in E-cadherin expression, IFNγ induced significant downregulation of total E-cadherin in benign RWPE cells and DU-H, DU-L, and PC3-H cancer cells." (PMID 35459800, 2022). "SNX-482 was also shown to upregulate the expression of CCR4 (C-C motif chemokine receptor 4), IFNG (IFN-gamma), GZMB (granzyme B) and PDCD1 (programmed cell death protein 1) genes, which are important for anti-cancer activity." (PMID 36119523, 2022). "In preclinical cancer models, efficacious ICI stimulates CD8+ T cells and IFNγ production thereby fortifying vessels with pericytes leading to increased perfusion." (PMID 35712656, 2022). "Treatment with IFNγ significantly increased both membranous and total expression of MHC-I and PD-L1 in benign RWPE cells as well as DU-H, DU-L, PC3-H and PC3-L cancer cells." (PMID 35459800, 2022). "Other cytokines such as interferon-gamma (IFN-γ) is capable of orchestrating numerous protective functions to heighten immune responses in infections and cancers." (PMID 35480398, 2022). "IRF1 represents a crucial transcriptional regulator of the IFNγ-response and recent findings on human cancers identified IRF1 as a central hub in cancer immunity." (PMID 34220848, 2021). "In cancer cells, SHP2 inhibition augmented interferon γ (IFNγ) signaling, which resulted in increased expression of its downstream targets, including chemoattractant cytokines and antigen presenting machinery." (PMID 33446805, 2021). "By producing interferon-gamma (IFN-γ), tumor necrosis factor-alpha (TNF-α), and granzymes, CTLs can destroy virus-infected cells and cancer cells." (PMID 34208346, 2021). "Therapies such as interferon gamma (IFN-γ), IL-2, and tumor necrosis factor (TNF-α), have been approved for cancer treatment." (PMID 34541363, 2021). "Conversely, CTLs indirectly target cancer cells via the secretion of cytokines, namely TNF-α and IFNγ, and the activation of cytotoxic macrophages and neutrophils." (PMID 34685635, 2021). "Plotting these pathways through their normalized ranks allows identifying the pan-cancer independent regulators of PD-L1 levels and EMT; for instance, TGFβ and NOTCH can be considered as more EMT-specific, while IFNγ and IFNα are PD-L1 specific modulators." (PMID 34975907, 2021). "As observed from previous reports of ANXA1 in different cancers, we also revealed that ANXA1 was mainly involved in immune-related functions, such as interferon-gamma response and regulation of innate immune response." (PMID 34912807, 2021). "Five of these signatures, including IFNα, IFNγ, STAT3, TGFβ and TNFα pathway signatures, are cancer immunity-related." (PMID 33767579, 2021).
cancer (continued). "Since IFNγ strongly induces NLRC5 gene expression, further studies in normal and cancer cells are needed to resolve the conundrum of STAT1-mediated gene activation and EZH2-mediated epigenetic repression of the same target genes." (PMID 33671123, 2021). "Activation of CTLs by heat shock protein (HSP70), ATP and high mobility group box1 (HMGB1) leads to the secretion of anticancer cytokines, such as interferon gamma (IFN-γ) and TNF-alpha which can induce apoptosis in cancer cells." (PMID 34470608, 2021). "IFNγ/STAT1-induced expression of caspases 1 and 8 has been reported in cancer cell lines, where STAT1 regulates Bcl-2 family members, including Bcl-xl, Bax, and Bak78–80." (PMID 34282238, 2021). "IFNγ is known to stimulate upregulation of CD74 protein in many cell types, including in cancer cells." (PMID 34944801, 2021). "More directly, our findings provided evidence that the expression of DKK1 was correlated with the level of Th1 markers (STAT1 and IFNG) and Th2 markers (GATA3 and STAT6) in various cancers, such as ACC, KICH, MESO, and PAAD." (PMID 34899842, 2021). "Three-dimensional spheroids made from cancer cells are a relevant system for investigating the interactions between cancer cells, macrophages, and the SFV/IFNg vector in this study." (PMID 34835178, 2021). "IFNg upregulates the expression of antigen presentation molecules, both MHC I and MHC II, stimulating the CTL response against cancer cells and an inflammatory Th1 adaptive response." (PMID 34835178, 2021). "In contrast, DNA demethylation and high expression of IFNγ and IL2 genes occur in both Th1 and CD8 T cells, which results in a better anti-cancer immune response." (PMID 33535484, 2021). "Furthermore, the commonly prescribed lipid-lowering atorvastatin had shown to diminish the PD-L1 induction by IFNγ alone or IFNγ/TNFα combination, implying that the use of atorvastatin might be helpful in developing therapeutic strategies to counter the immune evasion in cancers." (PMID 34445462, 2021). "CD8+ T cells secrete interferon gamma, regulate SLC3A2 and SLC7A11 expression, and promote cancer cell lipid peroxidation and ferroptosis." (PMID 34804371, 2021). "NKp30 is another activating receptor on the NK cells responsible for eliminating cancer cells and inducing dendritic cells maturation by secretion of tumor necrosis factor-alpha (TNF-α), interferon-gamma (IFN-γ), perforins and granzymes." (PMID 34046039, 2021). "For example, if a therapeutic aims to revive exhausted T cells, a 3D co-culture of cancer spheroids, CAFs, and immune cells could be developed and treated with compounds, and supernatants are assayed for cytokines indicative of immune activation, e.g., IL-2, IFNγ." (PMID 33564739, 2021). "We demonstrate that the core miRNA biogenesis and targeting machinery are essential for the IFNγ-activated JAK-STAT signaling and antigen presentation in cancer cells, largely by controlling miR-155-targeted silencing of SOCS1." (PMID 34853298, 2021). "TH1 cells produce interferon-gamma (IFN-γ) and are necessary for an effective response against intracellular infectious agents and cancer cells." (PMID 34571894, 2021). "To investigate the production of such metabolites from tryptophan in cancer cells expressing IDO1, we cultured cells with IFNγ in the presence of 13C11-tryptophan and performed liquid chromatography mass spectrometry (LC-MS) analysis." (PMID 33831358, 2021). "Theoretically, IFNγ‐induced increase in PD‐L1 and MHC class I expression as well as IFNγ‐induced decrease in NKG2D ligand expression in cancer cells attenuate NK cell‐mediated cytotoxicity." (PMID 33491334, 2021). "IFNγ release activates TMEM173/STING within neutrophils, which stimulates neutrophil-mediated killing of disseminated cancer cells in the lungs." (PMID 32849639, 2020).
cancer (continued). "Responsiveness to PD-1/PD-L1 checkpoint blockade correlates with an interferon gamma (IFNγ)-inducible gene signature and major histocompatibility complex class II (MHC II) expression by cancer cells." (PMID 32312906, 2020). "Interestingly, this score significantly correlated with many cancer hallmarks associated with immune response, including TNF-α signaling via NF-κB, IL2, and STAT5 signaling; IL6, JAK, and STAT3 signaling; inflammatory responses; IFNα response; and IFNγ response." (PMID 32988398, 2020). "With this experiment, they confirmed the existence of a significant accumulation of T cells around dendritic cells and cancer cell membrane treated with the MPLA-coated NPs and a significant induction of interferon gamma (IFNγ) secretion." (PMID 33218092, 2020). "These include TNFα, IFNγ, and TLR4, which are notorious mediators of muscle atrophy under conditions of experimental cancer cachexia." (PMID 33330108, 2020). "In one such report, Marjit and colleagues show that the combination of hypoxia and glucose deprivation prevents interferon gamma (IFNγ)-mediated upregulation of MHC-I in B16F10 and TC1 murine cancer cells." (PMID 32316260, 2020). "As it has been reported that CD40L induces maturation of DC for enhancing immune responses against cancer, the CD40L gene was used instead of IFNγ, and the therapeutic effect was examined." (PMID 32123853, 2020). "Research emphasizes the critical role of humoral factors secreted by cancer cells in the patient’s tissues in the regulation of processes leading to cachexia, which also include pro-inflammatory cytokines IL-6, TNF-α, IFNγ, IL-1α, and IL-1β." (PMID 33158194, 2020). "In type I, there is an initial antitumor immune response, in which perforin, granzyme, and interferon gamma (IFN-γ) are released by activated CD8+ cells, resulting in an immune attack on the cancer cells." (PMID 32349374, 2020). "Initially, CD8+ CTLs and CD4+ T helper cells can limit cancer development by production of IFNγ and cytotoxins, but many mechanisms including an immunosuppressive TME and chronic inflammation can override these effects to promote cancer development." (PMID 32937961, 2020). "GPR18 showed higher correlation coefficients with all three CYT, Teff, and IFNG scores than MS4A1 in the nine GPR18-prognositc cancer types, as well as 19 additional cancer types (except for DLBC)." (PMID 32398659, 2020). "While Group 1 ILC subsets are considered to play an important role in cancer regulation due to their similarity to CD4 Th1 cells and production of IFNγ, their involvement and function in metastasis is rather unclear." (PMID 32625207, 2020). "NK cells cytotoxic effects against cancer cells is mediated by NKG2D and IFNγ upregulation and induction and are enhanced in the presence of IL2." (PMID 31457012, 2019). "Whereas IFNγ and TNF are canonical pro-inflammatory cytokines, IL-2 has attained a more dichotomous role in cancer immunotherapy, with T cell stimulatory capacities on one hand and immunosuppressive characteristics on the other hand." (PMID 31195686, 2019). "JNJ-605 also strongly counteracted the induction of PD-L2 by IFNγ: upon 48 h of treatment, the ligand exposed at the surface of EBC-1 and Hs746T cancer cells returned to basal levels." (PMID 30723303, 2019). "NK cells activation for cytokine secretion was associated with upregulation of KIR2DL genes while the cytotoxic activation effect of NK cells against cancer cells correlated with NKG2D upregulation and induction of IFNγ and NO production." (PMID 31457012, 2019). "On the other hand, PD-L1 expression can be induced by interferon gamma (IFN-γ) and thus indicate the CTL in tumors and should be a favorable prognostic factor in cancer." (PMID 31523194, 2019). "Autophagy has also been shown to contribute to the anti-proliferative activity of interferon gamma (IFN-gamma), a pleiotropic cytokine that facilitates anti-viral and anti-proliferative effects in cancer cells." (PMID 30695997, 2019).
cancer (continued). "After gene set enrichment analysis, we determined that the IFNγ signaling pathway was up-regulated in CMT167 cancer cells relative to LLC cells in vivo, suggesting that these cells have a differential response to IFNγ." (PMID 31133614, 2019). "Fractalkine, GRO, IFNα2, IFNγ, IL-4, and MDC are also thought to play a role in the development of cancer cachexia." (PMID 30513792, 2018). "Strong ex vivo responses against arginase peptide were detected in IFNγ ELISPOT and arginase-1 specific CD4+ and CD8+ memory T cells were found in both healthy donors and cancer patients." (PMID 30400835, 2018). "Among the genes that we found down-regulated are: GZMA, GZMB, HLA-A, -B, -C and IFNG, all supporting a model of impaired CD8 T cell cytotoxic activities, one of the most important anti-cancer responses." (PMID 29928478, 2018). "We characterized spontaneous immune responses against optimized 38-mere arginase-1-derived peptide epitope in cancer patients and healthy donors using ex vivo and in vitro IFNγ ELISPOT and intracellular staining for IFNγ and TNFα." (PMID 30400835, 2018). "OCT1 is also reported to be overexpressed in many cancers, including CRC and the IFNγ promoter has been reported to contain a binding site for Oct proteins." (PMID 29408916, 2018). "Some genes are important factors in the immune system of cancer patients, such as CCL2, CCL20, CCL5, CCR7, IFNG and P450 family." (PMID 28384236, 2017). "The absolute need for local IFNγ to enable cytotoxic CD8 T-cell function is of significance for immunotherapy for chronic viral infection and for cancer." (PMID 28569770, 2017). "Regardless of clinicopathological characteristics, significant expression differences were observed, including 10 upregulated genes (CCL4/18, CXCL1/10/11, IFNγ, IL2/6/12A, VEGFA) and 1 downregulated gene (HLA-A) in lymphocytes from malignant ascites." (PMID 28620375, 2017). "Using knockout and a chemical inhibitor, our data show that JAK2 was necessary for IFNγ-induced IRF1 and cancer cell surface expression of HLA-ABC MHC class I molecules." (PMID 28977839, 2017). "IRF-1 lies immediately upstream of PD-L1 in the IFNγ-driven JAK/STAT signaling cascade, and has been shown to play a central role in regulating cancer cell’s response to IFNγ." (PMID 28331615, 2017). "As with the HDs, avelumab enhanced antigen-specific responses in a subset of the cancer patients, with three out of seven patients displaying an increase in CD8+ T cells that produced IFNγ and/or expressed the degranulation marker CD107a." (PMID 27350882, 2016). "HLA-DR, the primary antigen-presenting molecule of the MHC-II pathway is expressed in some cancers, particularly in response to CTL-secreted interferon-gamma (IFNγ)." (PMID 26822383, 2016). "Human cancer tissue microarray analysis indicated that MUC16 expression directly correlates with TNFα and IFNγ staining intensities in certain cancers." (PMID 26918940, 2016). "With the exception of IFNγ-induced IDO, all other evasion factors were studied at levels in transfected CHO cells that by far exceeded those found in six human cancer cell lines." (PMID 26510188, 2015). "Among these various Th subpopulations, the Th1 subset that produces interferon-gamma (IFN-γ), tumor necrosis factor-alpha (TNF-α) and interleukine-2 (IL-2), plays a clear antitumor role by orchestrating cell-mediated immunity against cancer cells." (PMID 26350591, 2015). "By using stably transfected CHO-EpCAM cell clones, we established expression levels for six evasion proteins that, with the exception of IFNγ-induced IDO, exceeded by far those found in six human cancer lines." (PMID 26510188, 2015). "CXCL10 is another pro-inflammatory chemokine that is released as a result of interferon gamma (IFN-γ) production and is responsible for monocyte and macrophage recruitment as well as some anti-cancer activities." (PMID 24736642, 2014).
cancer (continued). "We observed robust levels of IFNγ and TRAIL expression in GM-ADSCs conferring upon them the ability to be efficiently used for cancer therapy." (PMID 25428727, 2014). "COX-2 expression decreases the sensitivity of cancer cells to activated antigen-specific T cells by inducing the expression of IL4 and IDO, and by modulating the release of interferon-gamma by activated T cells." (PMID 25501829, 2014). "In cancer cachexia, systemic inflammation is induced and persists due to increased tumor necrosis factor-alpha (TNF-α), interleukin-6 (IL-6), IL-1, and interferon-gamma (IFN-γ)." (PMID 25050383, 2014). "Here we demonstrate for the first time in a cancer setting, the generation of inducible TReg cells from CD4+CD25- T cells where a subset produce IFNγ in vitro." (PMID 22666318, 2012). "We used mathematical modeling, simulations and parameter identifiability analysis to explain experimentally observed differences of IFNγ-induced STAT1 signalling in pancreatic stellate cells and cancer cells." (PMID 23284277, 2012). "Correlated parameters and parameters with one finite confidence interval helped to explain differences between IFNγ-induced STAT1 signalling in stellate and cancer cells." (PMID 23284277, 2012). "The present work is motivated by the following consideration: We observed differences in the trajectories of the parameterized models describing the IFNγ-induced STAT1 signalling pathway in PSC and cancer cells." (PMID 23284277, 2012). "The regulatory function, which is dependent on IFNγ, also results in the upregulation of MHC class II on macrophages, demonstrating a shift towards the anti-cancer M1 phenotype." (PMID 21674047, 2011). "Assay development studies (IFNγ Real Time RT-PCR and ELISPOT, HLA-A2 Tetramer analysis) and monitoring specific vaccine response in cancer patients are described by a number of investigators." (PMID 18945350, 2008). "Among those significantly increased with BRAF+/−MEKi were 14 of 17 genes of a Th1 signature associated with immunologic rejection of cancer, with GNLY, IFNG, and GBP1 the only genes not represented." (PMID 41514118, 2026). "Furthermore, our analysis identified three ferroptosis‐related genes, including IFNG, KEAP1, and PHKG2, as key biomarkers in prognosis prediction and potential targets for OV cancer therapy." (PMID 40744688, 2025). "Additionally, serine/glycine starvation decreased the expression of interferon γ (IFNγ) and granzyme B (GzmB) in OT-1 T cell co-cultures with multiple OVA-expressing cancer cell lines." (PMID 40389477, 2025). "We initially evaluated the efficacy of PD-L1 mRNA knockdown by siPDL1 and lipid-siPDL1s in cancer cells without IFNγ stimulation." (PMID 40001596, 2025). "In addition, co-administration of pablizumab (an PD-1 inhibitor) with CAR-T cells has also been found to restore the production of interferon-gamma (IFN-γ) and tumor necrosis factor-alpha (TNF-α) which can further facilitate anti-cancer immunity." (PMID 41024300, 2025). "Our approach was designed to be effective regardless of mRNA and protein levels, cancer cell type, or changes in expression levels upon IFNγ stimulation." (PMID 40001596, 2025). "We made use of the EGFRmut NSCLC persister model PC9, which has tunable low or high STAT1 pathway activity in the absence or presence (respectively) of IFNγ stimulation and was used in the initial discovery of the type I PRMT vulnerability in persistent cancer cells." (PMID 39699269, 2025). "PVD-06 was shown to induce significant TCPTP degradation in various cell lines, in a dose-dependent manner and, consequently, promoted T cell proliferation, amplified IFNγ signaling and inhibited melanoma B16F10 cell growth, thus exhibiting a potential for cancer immunotherapy." (PMID 41302504, 2025).